BRAF (B-Raf proto-oncogene, serine/threonine kinase)
Diseases named in the same sentence as BRAF in open-access papers (continued):
Sharing a sentence is not in itself a finding about the gene and the disease.
melanoma (continued). "Glucose metabolism is regulated by oncogenic BRAF through hypoxia inducible factor 1 alpha (HIF-1 alpha), avian myelocytomatosis viral oncogene homolog (c-Myc), and microphthalmia-associated transcription factor (MITF), and BRAF-mutated melanomas exhibit increased glycolysis." (PMID 40211360, 2025). "Notably, after TRIM63 depletion, the oncogenic effect of TRIM63 exhibited significant alterations exclusively in melanoma cells harboring BRAF mutations, while no such changes were observed in cells without BRAF mutation." (PMID 41315179, 2025). "Esto fue demostrado en un ensayo clínico de fase 3, realizado en pacientes a los que se les había resecado un melanoma en estadio III con mutaciones BRAF V600E o V600K con 12 meses de terapia adyuvante (dabrafenib + trametinib) en los que se logró una mayor sobrevida libre de enfermedad." (PMID 40977817, 2025). "Although specific evidence in the setting of BRAF V600–mutated melanoma is currently lacking, these agents may represent a potentially valuable adjunct for CV prevention." (PMID 40507236, 2025). "There are also reports that, unlike canine melanoma, canine prostate may harbor BRAF mutations and may be sensitive to docetaxel treatment." (PMID 41012800, 2025). "Although BRAFV600E-mutated MPNSTs are rarely reported clinically, their true prevalence may be underestimated, as BRAF status is often used diagnostically to favor melanoma over MPNST, and some amelanotic melanomas, especially the spizoid subtype, are molecularly challenging to diagnose." (PMID 41063628, 2025). "Second, the singular focus on KRAS-centric pathways, although justified by emerging evidence of KRAS involvement in some melanomas, may overlook synergistic or compensatory signaling through parallel oncogenic axes such as those governed by BRAF, NRAS, or PI3K-AKT-mTOR." (PMID 40607411, 2025). "Negative staining for HMB45, PNL2, and the absence of a BRAF V600E mutation help exclude melanoma." (PMID 41179672, 2025). "Surprisingly, this association could not be detected in BRAF-wildtype melanoma patients who received ICI." (PMID 40028330, 2025). "Moreover, the activation of the B-Raf proto-oncogene (BRAF) due to mutation by the oncogene v-RAF leads to increased p16Ink4a expression, positive senescence-associated beta-galactosidase staining, and stagnation of melanoma cell growth." (PMID 40149983, 2025). "BRAF mutation is more frequently found in superficial spreading melanoma/low-cumulative sun damage (Low-CSD) melanomas arising on non-chronic sun-damaged skin; differently, NRAS mutation is more frequent in nodular type and melanoma arising on chronic sun-damaged skin." (PMID 40867317, 2025). "Furthermore, baicalein has potential as a therapeutic agent against BRAF-mutant melanoma." (PMID 39790031, 2025). "Also, the ability of MAPK to trigger the expression of PD-L1 in melanoma cells conferring resistance BRAF inhibitors has been reported, suggesting that the inhibition of MAPK pathway may overcome MM resistance to immunotherapy." (PMID 41369373, 2025). "Similarly, in BRAF-mutant melanoma, PDX models resistant to BRAF and MEK inhibitors exhibited alternative activation of the mammalian target of rapamycin (mTOR) pathway, suggesting that mTOR inhibitors could be a viable treatment option for these patients." (PMID 41050078, 2025). "However, melanoma can occur on non-UV exposed surfaces (acral regions, mucosal surfaces, or even in the eye): in these cases, the characteristic BRAF mutation is less frequent and the so-called UV-signature mutations are also not typical." (PMID 40361349, 2025). "Additionally, in patients with BRAF V600-mutant melanoma, the triple combination of vemurafenib, cobimetinib, and XL888 demonstrated significant antitumor activity, including an ORR of 76%, median PFS of 7.6 months, and OS of 41.7 months; however, frequent dose adjustments were required." (PMID 40872476, 2025).
melanoma (continued). "Adjuvant BRAF and MEK inhibitors may be favored over standard-of-care adjuvant IO in patients with BRAF-mutated melanoma without a significant PR." (PMID 40647451, 2025). "Although we demonstrated the less cytotoxic effects to ArcA on melanoma with wild-type BRAF using B16F10 cell lines, there are limitations related to species differences, which complicate the interpretation of sensitivity variations by ArcA based on BRAF mutation status." (PMID 39948552, 2025). "Furthermore, in the BRAF-mutated melanoma population, anti-PD-1 monotherapy was also not approved, with BRAFi/MEKi being the only therapeutic option in the 1L setting." (PMID 40027067, 2025). "However, the absence of melanoma markers, including HMB45 and Melan-A, and the negative molecular profile for any melanoma-associated genetic alterations, including BRAF, NRAS, and NF1 gene alterations, argued against such an entity." (PMID 40978976, 2025). "Thus, the mutational profile of melanomas varies with age, so older patients tend to have more NRAS (NRAS proto-oncogene GTP-ase/Neuroblastoma RAS Viral (v-ras) Oncogene Homolog) mutations, while younger have more BRAF mutations." (PMID 41470117, 2025). "Notably, increased levels of HDAC8 in the cytoplasm of patients with metastatic BRAF-mutant melanoma were correlated with better survival, and the HDAC8 localization within tumor cells seems to be important for its biological effects, either positive or negative, on the cancer patient." (PMID 39935431, 2025). "Therefore, we speculated that A375 melanoma cells harbour BRAF V600E mutation, whereas SK-MEL-2 cells characterised by wild-type BRAF." (PMID 40636307, 2025). "Despite preclinical studies suggesting that dual MAPK inhibition or monotherapy with BRAF or MEK inhibitors may be effective against class II BRAF mutations in melanoma, these approaches are not standard in NSCLC." (PMID 40332392, 2025). "Additionally, RAC1P29S inhibits invadopodia function, abolishes haptotaxis, drives dedifferentiation in melanoma, contributes to BRAF inhibitor resistance, and facilitates immune evasion via programmed death-ligand 1 (PD-L1) upregulation through the RAC1P29S-PAK1 axis." (PMID 41034404, 2025). "In addition, a study found that peroxisomal FAO (pFAO) in BRAF-mutated melanoma persister cells was up-regulated through the PPARα-PGC1α-ACOX1 axis, and the use of pFAO inhibitors combined with BRAF/MEK inhibitors to treat melanoma delayed the emergence of resistance to targeted therapy." (PMID 40514365, 2025). "Additionally, c-JUN induces an EMT-like phenotype switch that may be responsible for the adaptive resistance to BRAF-MEK-ERK pathway inhibition in BRAFV600E melanoma cells." (PMID 40481178, 2025). "The contribution of copper to the activation of the BRAF/MEK/ERK signaling pathway in melanoma was demonstrated by the finding that the downregulation of SLC31A1 or mutations in MEK1, which disrupt copper binding, resulted in decreased levels of phosphorylated ERK in BRAF-mutant melanomas." (PMID 39970778, 2025). "Collectively, the current worrisome scenario concerning melanoma relates to a therapeutic arsenal that is no longer effective against resistant BRAF mutant metastatic melanoma and associated limited possibilities to improve patients’ conditions and rates of survival." (PMID 40244045, 2025). "We focused on the detection of specific cancer markers from malignant melanoma, using the BRAF gene (gene B of Rapid Acceleration of Fibrosarcoma) using RNA targets isolated by a simple nucleic acid extraction step from natural samples, such as tissue culture melanoma cells." (PMID 40277531, 2025). "Targeting this interaction may therefore sensitize BRAF-mutant melanoma to MAPK inhibition." (PMID 39636745, 2025).
melanoma (continued). "Notably, the combination of nivolumab and ipilimumab has demonstrated numerically superior progression-free survival (PFS) and overall survival (OS) compared to nivolumab alone (although this was an exploratory comparison), with particular benefit in patients with BRAF-mutant melanoma." (PMID 40758471, 2025). "Genetic studies have identified common mutations in melanoma, including cyclin-dependent kinase inhibitor 2A (CDKN2A), neuroblastoma rat sarcoma viral oncogene homolog (NRAS), phosphatase and tensin homolog (PTEN), and BRAF, with the latter being the most frequent oncogenic mutation." (PMID 40868149, 2025). "The most prevalent mutation is BRAF V600E, a valine-to-glutamate substitution in the kinase domain, leading to a constant protein kinase activation, including MEK/ERK signaling cascade, resulting in melanocyte hyperproliferation and contributing to melanoma development." (PMID 39795195, 2025). "Based on analyses of human melanomas, mouse models, and cell lines, gene expression signatures have been proposed to define cell states that have been variously categorized as pigmented, invasive, proliferative, neural crest (NC)-like, mesenchymal, intermediate, and BRAF inhibitor resistant." (PMID 40571713, 2025). "Notably, two patients with phenotypically heterogeneous tumours harbouring MAP2K1D67N mutations had additional BRAF and NRAS mutations: one with a melanocytoma containing BRAFV600E and NRASQ61R, and another with a melanoma containing BRAFG469R and NRASQ61R mutations." (PMID 40107205, 2025). "Interestingly, mutations in the gene encoding the BRAF protein are predominantly observed in melanomas arising in body regions only intermittently, rather than persistently, sun exposed, with a superficial spreading melanoma phenotype." (PMID 40725022, 2025). "While the interaction between GM and targeted therapies in melanoma is underexplored, early evidence suggests that BRAF inhibitors may promote immune activation by reducing immunosuppressive molecules and cytokines within the TME and enhancing CD8 + T-cell cytotoxicity." (PMID 40659866, 2025). "Lastly, BRAF mutations, considered the most common in cutaneous melanoma and significant therapeutic targets, remain rare in dedifferentiated lesions, as none of the rhabdomyosarcomatous melanomas harboured this modification." (PMID 40506928, 2025). "Indeed, previous studies primarily focused on BRAF-mutant melanoma cells." (PMID 40943167, 2025). "The phase III DREAMSEQ trial included 265 patients with treatment-naive BRAF V600-mutated metastatic melanoma, stratified by Eastern Cooperative Oncology Group PS 0 or 1 and lactate dehydrogenase (LDH) level; patients with untreated melanoma BMs (MBMs) were excluded." (PMID 39550033, 2025). "Moreover, in cancers such as melanoma, FDA approval of atezolizumab (programmed cell death ligand 1 [PD-L1] inhibitor), cobimetinib (MEK inhibitor), and vemurafenib (BRAF V600E inhibitor) for advanced BRAF V600-mutated melanoma illustrates the value of combining these modalities." (PMID 40707733, 2025). "However, it is genetically distinct, lacking melanoma-associated BRAF mutations and instead featuring recurrent and characteristic chromosomal translocations involving the EWSR1 gene." (PMID 40260360, 2025). "Also, regarding this issue, the presence of pre-operative ctDNA, assessed by ddPCR detecting BRAF and NRAS mutations, was detected in 34% of 119 patients with stage III melanoma who underwent CLND, and was significantly associated with tumor burden and worse MSS." (PMID 39859576, 2025).
melanoma (continued). "Considering the potential benefits, combining the conversion of global hypomethylation to hypermethylation in melanoma with other targeted therapies like molecularly targeted tyrosine kinase inhibitors (TKIs), BRAF, MEK, etc. could enhance treatment efficacy for patients." (PMID 38555324, 2024). "Also, early trials have shown that melanoma variants with and without BRAF-V600E mutation show promising tumor response to ICI therapy." (PMID 39682188, 2024). "However, recent advances in melanoma biology have led to newer therapies, such as immune checkpoint inhibitors (ipilimumab, nivolumab, pembrolizumab) and targeted BRAF/MEK inhibitors, which have proven effective in prolonging recurrence-free survival and improving patient outcomes." (PMID 39594665, 2024). "Finally, other potential targets emerging on BRAF/MEK-resistance were reported in melanoma patients, which may open further treatment options." (PMID 39684685, 2024). "There have been very few studies investigating BRAF V600E mutation status and odds of objective imaging response to ICI, and to our knowledge we are among the first to report this association in a real-world cohort of patients with advanced melanoma receiving first-line ICI therapy." (PMID 38884085, 2024). "With only a few studies identifying potential biomarkers for response to BRAF-targeted therapy, we set out to determine whether aneuploidy within the collected melanoma tumor tissue might predict the success of BRAF-targeted treatment or immunotherapy and overall disease response." (PMID 38473384, 2024). "However, ultraviolet (UV) irradiation triggers mutagenesis, and BRAF (v-raf murine sarcoma viral oncogene homolog B1) has high frequency hotspot mutation in human melanoma but is not characteristic of canine melanoma." (PMID 39408717, 2024). "Out of all patients, most (31/47 [66%]) did not remember whether their melanoma was assessed for BRAF mutations." (PMID 39624750, 2024). "BRAF-mutant melanoma was associated with younger age and location of nonsun-exposed skin." (PMID 39735251, 2024). "Furthermore, eosinophils induced apoptosis of melanoma cells, which might be increased by further treatment with BRAF/MEK inhibitors." (PMID 39126091, 2024). "Hence, targeting the positive feedback loop of p300-NONO-CRAF/ARAF-pERK1/2 may be an effective strategy to overcome the resistance of BRAF inhibitors for melanoma patients." (PMID 38493226, 2024). "BRAF V600 mutations are common in melanoma, thyroid, and non-small-cell lung cancers." (PMID 38333370, 2024). "These inhibitors may also warrant further investigation in subsets of Class 3 BRAF mutant melanoma." (PMID 38275886, 2024). "Indeed, several preclinical studies have shown that in a murine model of BRAF-mutated melanoma, treatment with BRAF inhibitors improves the antitumor effects of TCR-engineered ACT, increases the expression of melanoma-associated antigens, and decreases the expression of immunosuppressive cytokines." (PMID 39086722, 2024). "In patients with stage IV melanoma, immune checkpoint inhibitors are the preferred first-line treatment regardless of BRAF mutational status, and advanced melanoma patients carrying BRAF V600 mutation can also benefit from BRAF + MEK inhibitor treatment in certain cases." (PMID 39272837, 2024). "By contrast, high-CSD melanomas do not harbor BRAF V600E mutations but present other mitogen-activated protein kinase (MAPK) pathway mutations, such as BRAF V600K, NRAS G12/G13, or KIT mutations, or inactivation of the negative regulators of Ras, such as NF1 or RASA2." (PMID 38396984, 2024). "We were unable to classify the risk of BRAF and MEK cardiotoxicity according to the Heart Failure Association (HFA)-International Cardio-Oncology Society (ICOS) tool as the patient did not have echocardiography or cardiac markers examined before the start of treatment of the melanoma." (PMID 39583362, 2024).
melanoma (continued). "Additionally, BRAF mutation (V600E) suppresses MITF and PGC1α expression in melanoma cells." (PMID 38774408, 2024). "Analysis of over 80,000 human tumours found somatic BRAF mutations present in 4.6% of samples, most commonly occurring in hairy cell leukaemia (72%), thyroid cancer (45%), melanoma (36%), histiocytosis (19%), colorectal cancer (12%), and non-hairy cell leukaemia mature B cell neoplasms (3%)." (PMID 38787171, 2024). "Additionally, targeted combination therapy has been found to be particularly successful in preventing relapse and death in certain melanoma patients, achieving 20% lower risk of death with stage III patients and 25% lower BRAF V600E mutation patients compared to the placebo." (PMID 39682188, 2024). "Furthermore, we found that BRAF V600 mutant primary melanoma that localizes to the extremities or invades the subcutaneous tissue may represent distinct melanoma subtypes that merit further investigation." (PMID 39272837, 2024). "Furthermore, primary melanomas with BRAF V600E mutations had fewer TPMs than those without (77.8 vs. 93.8%, P = 0.024, Fisher's exact test)." (PMID 38371417, 2024). "A peculiar role of NONO has been described in nearly half of melanoma patients carrying the mutation V600E in the BRAF kinase; for this subset of patients, BRAF inhibitors show a significant antitumor response, but the common emergence of acquired resistance remains a challenge." (PMID 38493226, 2024). "The present study suggests that clinicopathological factors, including primary tumor characteristics and stage of metastatic disease, as well as serum markers may provide information on the probability of survival in patients with advanced melanoma treated with BRAF and MEK inhibitors." (PMID 39272837, 2024). "However, the presence of a BRAF mutation alone often does not lead to melanoma, as many nevi with this mutation tend to remain stable and do not progress to a malignant state." (PMID 38534742, 2024). "In addition, SAMMSON can modulate epigenetic processes by regulating histones or DNA methylation, which is significantly upregulated in cancer; it also induces melanoma cells to develop drug resistance to BRAF inhibition by increasing oxidative phosphorylation." (PMID 39659781, 2024). "Examples include cancers such as malignant melanoma with BRAF variants, ovarian carcinomas with BRCA alterations and non-small cell lung carcinoma, where the list of targeted treatments is ever expanding but already includes EGFR, ALK, ROS-1, NTRK, MET, RET, BRAF, and KRAS." (PMID 38850363, 2024). "Moreover, multiple BRAF alterations were detected in melanoma patients." (PMID 39582535, 2024). "BRAF V600 mutation analysis is required for treatment decision guidance in patients with distant or inoperable regional metastases and in patients with resected high-risk stage III melanoma, given the approval of BRAF and MEK inhibitors in the adjuvant setting." (PMID 38541077, 2024). "Taken together our findings have profound translational implications because we identified a new MITF/miR-579-3p regulatory network that impacts on melanoma proliferation, differentiation and drug resistance and whose targeting may provide a novel therapeutic strategy for BRAF-mutant melanomas." (PMID 38472212, 2024). "However, although the targeting of both BRAF and MEK has been used as a standard treatment approach for patients with melanoma harbouring BRAF V600 mutations the challenge still remains because of the variable patient responses to that combination and of drug resistance." (PMID 38182748, 2024). "BRAF V600 mutations, the most common mutations in melanomas, are absent in Spitz tumors." (PMID 39335684, 2024). "However, resistance to dabrafenib commonly occurred in patients with BRAF-mutant melanoma." (PMID 38594618, 2024).